TRPV6 (transient receptor potential cation channel subfamily V member 6)
Diseases named in the same sentence as TRPV6 in open-access papers (continued):
Sharing a sentence is not in itself a finding about the gene and the disease.
triple-negative breast carcinoma (1 paper, 2025). An invasive breast carcinoma which is negative for expression of estrogen receptor (ER), progesterone receptor (PR), and human epidermal growth factor receptor 2 (HER2). "The expression of calcium-related proteins varies among cancer subtypes; for instance, TRPV6 overexpression is significantly associated with the triple-negative breast cancer subtype due to increased TRPV6 gene copy numbers." (PMID 40433361, 2025).
trisomy 16 (1 paper, 2022). "We analyzed the methylation indices of the promoter regions of 5 DMGs (ANKRD53, TRPV6, GATA3-AS1, SCL13A4, and CALCB) in chorionic villi trophoblasts of miscarriages with trisomy 16 and induced abortions with a normal karyotype using targeted bisulfite massive parallel sequencing." (PMID 35064135, 2022).
vestibular disorder (1 paper, 2025). Pathological processes of the vestibular labyrinth which contains part of the balancing apparatus. "Additionally, Klotho downregulation decreases transient receptor potential vanilloid 5(TRPV5) and TRPV6 levels, altering inner ear Ca2+ regulation and causing sensory cell transduction defects that manifest as auditory or vestibular disorders." (PMID 40737282, 2025).
cancer (84 papers, 2008 to 2026). A tumor composed of atypical neoplastic, often pleomorphic cells that invade other tissues. "Given that dysregulation of TRPV6 is associated with various diseases, including different types of cancer, there is a compelling need for its pharmacological targeting." (PMID 38203789, 2024). "The upregulation of TRPV6, on the other hand, is associated with cancer progression, as it contributes to promoting cell proliferation and inhibiting cell apoptosis, and it is overexpressed in a variety of human cancers." (PMID 39742020, 2024). "Because calcium is so important in the formation of cancer, TRPV6 has also been classified as a tumor channel implicated in enhanced cell proliferation and the prevention of apoptosis." (PMID 38534438, 2024). "The unusual mechanism of TRPV6 inhibition by genistein lays the foundations for the development of much-needed new drugs targeting TRPV6-associated diseases, including cancers." (PMID 37160865, 2023). "Accordingly, suppression of TRPV6 activity was proposed to underlie cancer protective effects in the colon when following a calcium-rich diet." (PMID 37838981, 2023). "When the normal TRPV6 function is disturbed, it causes changes in calcium homeostasis, leading to various human diseases, including different forms of cancers." (PMID 37838981, 2023). "Since calcium uptake is linked to cell proliferation and cancer progression, TRPV6 was also declared an oncochannel." (PMID 37160865, 2023). "Future studies would determine the role of TRPV6 with an associated regulatory pathway in other cancers." (PMID 34413465, 2021). "TRPV6 inhibitors are needed for the treatment of a broad range of diseases associated with disturbed calcium homeostasis, including cancers." (PMID 34725357, 2021). "Transient receptor potential vanilloid 6 (TRPV6) is a calcium channel implicated in multifactorial diseases and overexpressed in numerous cancers." (PMID 33479695, 2020). "Related to cancer invasion, abnormal Ca2+ homeostasis has been associated with epithelial mesenchymal transition and we also detected an interdepency in between TRPV6 expression and the levels of many EMT-associated factors." (PMID 32895467, 2020). "Overexpression of TRPV6 has been linked to several cancers of epithelial origin, including prostate, breast, ovary, colon and pancreatic cancers." (PMID 32895467, 2020). "Calcium uptake in epithelial tissues is mediated by tetrameric calcium-selective transient receptor potential (TRP) channels TRPV6 that are implicated in a variety of human diseases, including numerous forms of cancer." (PMID 29632318, 2018). "Studies in candidate cancer genes including EPHB6/TRPV6 found two SNPs in EPHB6/TRPV6 marginally associated with survival in CRC." (PMID 29299148, 2017). "Consequently, TRPV6 inhibitors have the potential to treat a wide range of illnesses, including TRPV6-rich cancers, that are linked to abnormalities in calcium homeostasis." (PMID 38534438, 2024). "The TRPV6 channel is upregulated in many cancers and is associated with bad prognosis." (PMID 36980711, 2023). "Thus, overexpression of TRPV6 transcripts is associated with several malignancies, which include cancer derived from prostate and breast." (PMID 34884497, 2021). "TRPV6 (transient receptor potential cation channel subfamily V member 6 or transient receptor potential vanilloid 6) is expressed in the placenta, epidermis, digestive tract, and salivary glands, and its dysregulation is associated with several diseases, including cancer." (PMID 37408210, 2023). "However, other mutations outside the CaMBD domain or different mutations inside the CaMDB domains are also likely to be involved in deleterious phenotypes, as suggested by the variety of non-synonymous mutations associated with TRPV4 and TRPV6 in the COSMIC cancer database." (PMID 32186440, 2020).
cancer (continued). "Among the Ca2+ channels, TRPV6 has emerged as a key regulator since this channel is highly selective for Ca2+ and frequently overexpressed in different types of cancers." (PMID 42193028, 2026). "Since calcium uptake plays a role in cell proliferation and cancer progression, TRPV6 is recognized as an oncochannel." (PMID 41198662, 2025). "One of these channels, TRPV6, has its role already well established in human cancerogenesis and was shown to be involved in many cancers of organs such as prostate, breast, colon, thyroid, ovary, and many others, being mostly described as a proto-oncogene." (PMID 38879621, 2024). "In particular, TRPV6, ASIC2, MMP13, and FOXH1 are well known to be implicated in cancer development." (PMID 38457049, 2024). "This review will summarize the function of TRPV6 in regulating calcium signaling in cancer and its potential application as a cancer therapeutic target." (PMID 38534438, 2024). "Due to TRPV6′s critical function in the development of cancer, it is imperative to identify small molecule inhibitors and TRPV6 ion channel blockers as possible therapeutic targets." (PMID 38534438, 2024). "Due to reports that TRPV6′s mRNA and protein are overexpressed in several human cancers, the gene for TRPV6 has been classified as an oncogene, and the channel as an oncochannel." (PMID 38534438, 2024). "Nevertheless, TRPV6 is a prospective target in the treatment of PCa being absent in healthy prostate and increasing its expression as well as its occurrence with the cancer stage." (PMID 38879621, 2024). "Reduced cell proliferation and higher cell death are the results of RNA silencing, which diminish TRPV6 synthesis in cancer cell lines." (PMID 38534438, 2024). "The purpose of this review is to summarize the characteristics of the TRPV6 channels and their role in cancer, so as to determine the potential of TRPV6 in cancer treatments." (PMID 38534438, 2024). "The function of TRPV6 in regulating calcium signaling in cancer will be covered in this review, along with its potential applications as a cancer treatment target." (PMID 38534438, 2024). "Cancer cells can be prevented from migrating, invading, or surviving by the expression of TRPV6 knockdown, or by MCF-7, MDA-MB-231, and T-47D cell line inhibitors." (PMID 38534438, 2024). "The in vivo results obtained with mAb82 on tumors expressing TRPV6 in an immunodeficient mouse model enable us to obtain proof-of-principle for a monoclonal anti-cancer treatment targeting TRPV6." (PMID 38879621, 2024). "More precisely, the calcium channel TRPV6 alters the global transcriptomes of cancer cell lines and most notably the chemotaxis, migration, invasion, apoptosis, ferroptosis, drug resistance, and ECM organization pathways." (PMID 37576552, 2023). "As for rb79 and rb82, their binding to TRPV6 led to the transient activation of the latter while activating calcium currents and increasing capacitive calcium entry—deleterious for a cancer cell by inducing its death." (PMID 36980711, 2023). "Dysregulation of TRPV6 results in disturbed calcium homeostasis leading to a variety of human diseases, including many forms of cancer." (PMID 37838981, 2023). "Overall, TRPV6 channels promote cancer cell proliferation, survival, migration, and invasion by modulating intracellular Ca2+ signaling and downstream pathways." (PMID 38136316, 2023). "In the presence of TRPV6, different cancer cell lines decrease the expression of Orai2, a calcium channel participating in SOCE." (PMID 37576552, 2023). "Within this context, TRPV6, a calcium-permeable channel, emerges as a noteworthy candidate due to its overexpression in various cancers, capable of influencing the cell behavior in different cancer entities." (PMID 38136316, 2023). "Our results also show that TRPV6 expression influences therapy resistance and the migration of Panc-1 cells, two important features of cancer aggressiveness." (PMID 38136316, 2023).
cancer (continued). "The efforts to target the TRPV6 channel in vivo are still ongoing to propose an effective therapy against cancer." (PMID 36980711, 2023). "The calcium-selective oncochannel TRPV6 is an important driver of cell proliferation in human cancers." (PMID 37532722, 2023). "TRPV6, a calcium-permeable channel overexpressed in cancers, holds potential as an influencer of cancer cell behavior." (PMID 38136316, 2023). "Increasing evidence suggests that the overexpression of TRPV6 is a common event in cancers of epithelial origin." (PMID 36980711, 2023). "A small interventional phase I clinical trial (NCT01578564) tests the safety and tolerability of a TRPV6 inhibitor in subjects with advanced ovarian cancer or other cancers known to overexpress the TRPV6 channel." (PMID 37892239, 2023). "For example, TRPV5 and TRPV6 were down-regulated in most cancers, while TRPV2 and TRPV3 tend to be up-regulated in most cases." (PMID 35174089, 2022). "The first mention that the TRPV6 channel appears in some cancers, including PCa, emerged at the beginning of the 2000s." (PMID 36613866, 2022). "Tumours can be characterized by a more acidic extracellular microenvironment during late stages, phases in which TRPV6 expression is downregulated in some types of cancers, such as colon cancer." (PMID 35806388, 2022). "The relationship between TRPV6 and malignant transformation of various tissues has been extensively studied, and its expression level has been found to be elevated in many cancers, including breast cancer and pancreatic cancer." (PMID 36230965, 2022). "For example, TRPA1, TRPC1, TRPV4, TRPV5, and TRPV6 exhibited higher CNV amplification, while TRPV1, TRPV2, TRPV3, and TRPC3 exhibited frequent CNV loss in cancer." (PMID 35614079, 2022). "It has already been demonstrated that the overexpression of the TRPV6 calcium channel is a common event in cancers of epithelial origin." (PMID 36613866, 2022). "Overall, the increasing evidence suggests that the overexpression of the calcium channel TRPV6 is a common event in cancers of epithelial origin." (PMID 36613866, 2022). "By electrophysiology and Ca imaging in Xenopus oocytes and cancer cells, molecular biology and numerical simulation, here we reveal an intramolecular S5/S6 helix interaction in TRPV6 that is functionally autoinhibitory and is mediated by the R532:D620 bonding." (PMID 34413465, 2021). "Increased expression of TRPV6 stimulates the metastasis of cancer cells and confers chemotherapy resistance." (PMID 34356643, 2021). "Some Ca2+-permeable channels have been implicated in the enhanced migration of various cancers: TRPC1, TRPM7, TRPM8, TRPV1, TRPV2, TRPV6, STIM1, Ca2+-release activated Ca2+ modulator 1 (Orai1) and some types of VGCCs." (PMID 36046118, 2021). "Increased [Ca2+]i induces cell proliferation through TRPV6-mediated Ca2+ influx and TRPV6 inhibition, which are upregulated by sex hormones leading to T47D (hormone receptor-positive) cancer cell death." (PMID 33806911, 2021). "The role of TRPV6 has been extensively investigated upon malignant transformation in various tissues and its expression is known to be elevated in many cancers." (PMID 34356643, 2021). "TRPV6 is clearly a valid target to disrupt further the aberrant calcium homeostasis observed in and required by many cancers." (PMID 31897233, 2020). "This review compiles and updates recent published work on TRPV6 as a promising drug target in a number of cancers including those afflicting breast, ovarian, prostate and pancreatic tissues." (PMID 31897233, 2020). "A review of pharmacological approaches to exploiting TRP channel activity in cancer has been published 164 and a number of TRPV6 inhibitors are cited in a recent review of targeting calcium signalling in cancer." (PMID 31897233, 2020).
cancer (continued). "The evidence for the utility of TRPV6 inhibition in solid cancers has built over the last number of years in cancer cell lines, in xenograft murine models, and now has a suggestion of efficacy in humans." (PMID 31897233, 2020). "Depletion of TRPV6 decreased the levels of several EMT-markers in this cancer cell line, as detected by Western blot analyses." (PMID 32895467, 2020). "Transient receptor potential vanilloid 6 (TRPV6) is another TRP channel that has been suggested as a target for cancer." (PMID 32825277, 2020). "This is a preliminary study aimed to address the potential correlation between the different expression level of calcium receptors such as CaSR and TRPV6 and manganese uptake in different cancer animal models." (PMID 32931488, 2020). "The potential clinical relevance of TRPV6 channels in PDAC is further underpinned by observations from a phase I dose escalation study with the TRPV6 inhibitor SOR-C13 in cancer patients." (PMID 33841132, 2020). "It is now well established that a number of epithelial type cancers over-express TRPV6 mRNA and likely overproduce protein compared to healthy tissues." (PMID 31897233, 2020). "TRPV6 can be greatly elevated in a number of cancers deriving from epithelia and considerable study has been made of its role in the cancer phenotype where calcium control is dysfunctional." (PMID 31897233, 2020). "But, the role of Vitamin D is complicated further since TRPV6 also has a reciprocal role in how Vitamin D3 influences cancer." (PMID 31897233, 2020). "In this study, we aimed in deeper understanding on the role of TRPV6 in mammary epithelial homeostasis and cancer progression." (PMID 32895467, 2020). "Of the 23 patients enrolled in this study with cancers classed as “TRPV6-rich” >50% showed stable disease after two courses of treatment with no drug-related serious adverse events." (PMID 31897233, 2020). "TRPV6 has emerged as a target in cancer treatment because of its role in increasing intracellular calcium and initiating downstream signalling pathways that increase cell proliferation, metastasis and inhibition of apoptosis." (PMID 31897233, 2020). "Alongside TRPV6 and TRPV4, TRPV2 is a further vanilloid family receptor that has been implicated in cancer progression." (PMID 32825277, 2020). "Reduction of TRPV6 activity by decreasing expression of the channel or by pharmacological intervention has shown efficacy in four cancer types: adenocarcinomas of breast, ovarian, prostate and pancreas." (PMID 31897233, 2020). "On the other hand, TRPV6 expression was found to be abnormally upregulated in numerous cancers of breast and prostate tissues, compared to normal tissues." (PMID 33479695, 2020). "Due to the involvement of TRPV6 channels in cancer cell proliferation and its overexpression in numerous cancer models, attempts have been made to virtually screen TRPV6’s Ca2+ channel inhibitors." (PMID 31627357, 2019). "The TRP channel TRPV6 mediates calcium uptake in epithelia and its expression is dramatically increased in numerous types of cancer." (PMID 29941865, 2018). "The transient receptor potential channel TRPV6 mediates calcium uptake in epithelia and its expression is increased in several cancer types." (PMID 29941865, 2018). "In TRPV6 over-expressing cancer cells, both SOR-C13 and SOR-C27 are proved to inhibit calcium influx efficiently and reduce cell viability." (PMID 29246030, 2017). "Until that time SOR-C13 remains the first-in-class, high affinity and selective antagonist of TRPV6 to enter human trials as an anti-cancer agent." (PMID 28150073, 2017). "Pharmacodynamic assessments measured the plasma levels of ccK18, a caspase-cleaved cytokeratin produced during apoptosis, and circulating TRPV6 mRNA presumably from cancer exosome production." (PMID 28150073, 2017). "Colon cancer (SW480) and myelogenous leukemia (K-562) cell lines were the first cancer cells noted to express TRPV6 mRNA." (PMID 28150073, 2017).